ALOX5 (arachidonate 5-lipoxygenase)
Diseases named in the same sentence as ALOX5 in open-access papers (continued):
Sharing a sentence is not in itself a finding about the gene and the disease.
tumor (continued). "Importantly, neutrophil infiltration was significantly reduced in SAAHIGHALOX5HIGH tumours, to suggest that increased expression of ALOX5 in tumours may enhance SPM production to oppose the inflammatory actions of SAA." (PMID 34203378, 2021). "A pioneering approach involves CRISPR-based ALOX5/15 gene editing, which suppresses LTB4 production and inhibits tumor growth in preclinical CAC models, offering a targeted strategy to disrupt pro-tumorigenic inflammation." (PMID 41210682, 2025). "SDA inhibits the action of cyclooxogenase-2 (COX-2) and arachidonate 5-lypoxigenase (ALOX5), reducing prostaglandins (e.g., PGE2) and leukotrienes that enhance tumor growth." (PMID 40507897, 2025). "The findings revealed that C1 CALR+MCs, C2 ALOX5+MCs, C3 ANXA2+MCs, C5 IL32+MCs, myeloid cells, fibroblasts, and SMCs are capable of targeting tumor cells by releasing TWEAK." (PMID 39224598, 2024). "LTB4, a metabolite of ALOX5, binds to BLT1/BLT2 on the surface of TAM to activate the PI3K pathway, thereby promoting the migration of M2-type macrophages around the tumor." (PMID 39290697, 2024). "Ferroptosis analysis indicated that ALOX5 and VLDLR were the top CAPG-related ferroptosis markers; glutathione metabolism levels in tumor group were generally high, and decitabine was a ferroptosis inducer." (PMID 39600941, 2024). "LTB4, a metabolite of ALOX5, activates the PI3K pathway by binding to BLT1/BLT2 on the surface of TAMs, thereby promoting the migration of M2 macrophages around the tumor and ultimately facilitating the progression of iCCA." (PMID 39290697, 2024). "Twenty genes that were commonly upregulated by NTX-301 in the three different CCLs were involved in immune activation, and these genes included known tumor suppressors such as BTG2, ALOX5, SOCS1, and TP53INP1." (PMID 36980623, 2023). "Mean expression levels of COX1, COX2, ALOX5, ALOX5AP and correlated genes of the JAK STAT and Src pathways in adjacent tissues were similar to levels in the tumor samples." (PMID 37190308, 2023). "Subsequent experimental validation in vitro and in vivo revealed that the most significantly differentially expressed gene identified herein, ALOX5, was capable of suppressing RCC tumor cell proliferation, invasivity, and migration." (PMID 38090559, 2023). "Seven hub genes (AXL, EFEMP2, VIM, EHD2, FSTL3, ALOX5, HSPB8) were downregulated in tumor samples, while COL3A1 was upregulated in tumor samples in the TCGA dataset." (PMID 37291533, 2023). "The comparatively lower expression of AGXT, PTGER3 and SLC12A3 in tumours correlates with worse prognosis in KIRC patients, while higher expression of ALOX5 predicts reduced survival." (PMID 32144299, 2020). "As shown by IHC staining, the expressions of ALOX15 and ALOX15B were strikingly down-regulated, while ALOX5 and ALOX12 were strikingly up-regulated in tumor, compared with those in surrounding tissue." (PMID 31528237, 2019). "In addition, ALOX5 inhibition reduce the incidence of AAA and slow tumor growth after aneurysm formation in animal models." (PMID 40781109, 2025). "Platelet-type ALOX12 and ALOX5 have been widely studied to induce carcinogenesis while ALOX15 and ALOX15B exhibit anti-carcinogenic activities although several studies demonstrate dual roles in regulating tumor development." (PMID 38612771, 2024). "Furthermore, knockdown of ALOX5 augmented cell death in MDA‐MB‐231 cells in vitro, suggesting its key role in reducing tumour proliferation." (PMID 38140764, 2024). "In tumors derived from both cell lines, we found eicosanoid synthases (Ptgs1, Ptgs2, Hpgds, Alox5) to be more highly expressed in immune cells than in tumor cells although expression is not exclusive (Figure A3A and B; Table A2)." (PMID 36277993, 2022).
tumor (continued). "The protein level of ferroptosis-related genes was verified by the HPA database and IHC test, leading to the discovery that the expressions of ALOX5, PEBP1, ACSL4, and ZEB1 proteins up-regulated in tumor tissues, and existed differences between tumor tissues and normal tissues." (PMID 36313708, 2022). "Specifically, our in vitro results suggest that ALOX5 may be an oncogene, while ALOX12 and CISD1 may be tumor suppressor genes in PAAD." (PMID 35033072, 2022). "We next analysed the SAA/ALOX5 ratio and observed an increased ratio of SAA relative to ALOX5 mRNA levels irrespective of tumour genotype." (PMID 34203378, 2021). "In lung, ALOX5 may play a surveillance role for cells with CNA, as other researchers have suggested that ALOX5 inhibition can promote tumor development." (PMID 34070461, 2021). "Furthermore, the ALOX5/5-LO enzymatic product, AT-RvD1, markedly reduced the NLR and suppressed tumour growth in KrasG12D mice." (PMID 34203378, 2021). "Representative images of IHC analysis displayed the cytoplasmic/membranous staining of Alox5 and that the staining intensity was higher in tumor than normal samples." (PMID 34121352, 2021). "For instance, using WGCNA and a protein-protein interaction network, a recent study analyzed the gene expression pattern of 26 pairs of tumor tissues/adjacent tissues and identified four hub genes involved in the progression of KIRC, including AGXT, PTGER3, SLC12A3, and ALOX5." (PMID 33110456, 2020). "In contrast to the oncogenic role of ALOX5 reported previously in CML26, here we show that ALOX5, suppressed by PRC2 at the transcription level, exhibits a moderate anti-tumor effect both in vitro and in vivo in MLL-rearranged AML, in which ALOX5 expression is especially repressed." (PMID 28500307, 2017). "The expression of 5-LOX/ALOX5 in a GBM tumor is higher than in non-tumor brain tissue." (PMID 36765904, 2023). "Arachidonic acid 5-lipoxygenase (ALOX5) is an iron-containing non-heme dioxygenase that catalyzes the peroxidation of polyunsaturated fatty acids such as arachidonic acid and plays vital role in inflammatory responses, cell death, and tumor occurrence and development." (PMID 40781109, 2025).
cancer (150 papers, 2009 to 2026). A tumor composed of atypical neoplastic, often pleomorphic cells that invade other tissues. "Among Black women, increased risk was observed for ALOX5-rs1369214 (OR: 1.44, P = 0.003) in the recessive model and was stronger among premenopausal women (OR: 1.57, P = 0.03) and for ER+ cancer (OR: 1.53, P = 0.003)." (PMID 34249719, 2021). "Among Black women, an increased risk of ER+ cancer was observed for ALOX5-rs1369214 (OR: 1.53, 95% CI: 1.15–2.03) and ALOX5AP-rs9579648 (OR: 2.36, 95% CI: 1.15–4.84) in the recessive models." (PMID 34249719, 2021). "A reduced risk was observed for ALOX5-rs7099874 (OR: 0.75, P = 0.01) in the dominant model, and was stronger among postmenopausal women (OR: 0.68, P = 0.03) and for ER+ cancer (OR: 0.66, P = 0.001)." (PMID 34249719, 2021). "ALOX5 encodes 5-lypoxygenase (5-LO) that converts arachidonic acid into leukotrienes and is involved in inflammatory condition and cancer development." (PMID 34945101, 2021). "Arachidonate 5-lipoxygenase (Alox5) gene encoding arachidonate 5-lipoxygenase (5-LO) is involved in numerous physiological and pathological processes, including oxidative stress response, inflammation and cancer." (PMID 24252550, 2013). "ALOX5, an enzyme encoded by the ALOX5 gene known as 5-lipoxygenase, plays a crucial role in M2 macrophage polarization and is a useful druggable target for cancer treatment." (PMID 38891952, 2024). "Previous studies have shown that the high expression of ALOX5 is closely associated with ferroptosis sensitivity, and ferroptosis is also closely linked to chemoresistance in cancer cells, with chemoresistant cancer cells being more susceptible to GPX4 inhibition." (PMID 41184226, 2025). "Previous studies have documented that dysregulation of ALOX5 was correlated with ferroptosis resistance in various cancers." (PMID 39850123, 2025). "Although ALOX5 is best known for its role in lipid peroxidation and ferroptosis regulation, evidence also suggests its involvement in cancer stemness." (PMID 41184226, 2025). "Neutrophils isolated from pre-metastatic niches secrete leukotriene B4 (LTB4) that transforms heterogeneous cancer cell populations into metastasis-initiating cells and enhance the ability of metastasis through arachidonate 5-lipoxygenase (ALOX5) enzyme." (PMID 37158964, 2023). "Incubation of cancer cells with CM from macrophages treated with zileuton, an inhibitor of ALOX5, a rate-limiting enzyme of 5-oxo-ETE biosynthesis, resulted in a noticeable reduction in the previously enhanced migration." (PMID 38202807, 2023). "Genetic deletion or pharmacologic inhibition of the enzyme arachidonate 5-lipoxygenase (Alox5), which generates leukotrienes, suppresses the pro-metastatic activity of neutrophils and consequently decreases cancer metastasis." (PMID 36514901, 2022). "At the protein level, we found that the expression of ALOX5 was significantly more expressed in cancer tissues than in normal tissues (p < 0.001)." (PMID 35444656, 2022). "It has been proved that ALOX5 can stimulate the expression of oncogenes and promote mitosis and chemotaxis in various types of cancer cells." (PMID 36313708, 2022). "ALOX5 is a type of lipoxygenase and plays a pivotal role in inducing ferroptosis in various types of cancer cells." (PMID 34095228, 2021). "In other organs (e.g., colon, pancreas), ALOX5 inhibition with COX1/2 inhibitors shows cancer chemoprevention effects." (PMID 34070461, 2021). "For example, anti-asthma drug zileuton, an ALOX5 inhibitor, can reduce cancer metastasis in animal models by targeting pro-metastatic neutrophils." (PMID 33101283, 2020). "ALOX5 also played a crucial role in inflammation-related cancers like colorectal cancer, breast cancer, and glioma." (PMID 31871543, 2019).
cancer (continued). "Activation of FPR1 on cancer gastric cells reduced the local angiogenesis and cancer growth, depending on pro-resolving mediators of inflammation, such as metabolic activity of lipoxygenases (ALOX5/15)." (PMID 30250432, 2018). "Next, we examined the expression of acyl-CoA synthetase long-chain family member 4 (ACSL4), arachidonate 5-lipoxygenase (ALOX5), and arachidonate 15-lipoxygenase (ALOX15), which are implicated in lipid peroxidation, a major cause of ferroptosis in carcinoma cells." (PMID 41339896, 2025). "Aberrant expression of ALOX5 has been observed in various types of cancers, including PTC25." (PMID 38609408, 2024). "Furthermore, MGST1 exerts inhibitory effects on the process of ferroptosis in cancer cells by interacting with ALOX5, or its lipid peroxidase activities." (PMID 38169383, 2024). "Stimulation of cancer metastases may also occur through the production of the leukotriene-producing enzyme, arachidonate 5-lipoxygenase (Alox5), and transferrin." (PMID 39769334, 2024). "ALOX5 encodes a nonheme iron-containing dioxygenase of the lipoxygenase gene family that has been identified as a critical regulator of cancer stem cells from hematological malignancies." (PMID 37291533, 2023). "The effects of 5-LOX/ALOX5 on GBM cancer stem cells are autocrine in nature." (PMID 36765904, 2023). "In addition, ALOX5 is upregulated in gastrointestinal cancer and its overexpression is related to the cancer progression." (PMID 36777735, 2023). "Expression of 5-LOX/ALOX5 is higher in GBM cancer stem cells than in other GBM cancer cells." (PMID 36765904, 2023). "Inhibition of ALOX5 has a synthetic effect with COX-2 inhibitor on suppressing cancer cell growth." (PMID 36750552, 2023). "ALOX5 is an important lipid metabolism enzyme in cancer progression, but the mechanism by which it regulates TAM to promote ICC progression is unknown." (PMID 38124204, 2023). "ALOX5 was shown to regulate ferroptosis in cancer cells through lipid peroxidation." (PMID 35444656, 2022). "Levels of TFRC (P<0.001), PHKG2 (P=0.005), FADS2 (P<0.001), and NOX1 (P=0.011) mRNA relative expression were higher in cancer cells than in immune cells, whereas levels of ALOX5 (P<0.001) mRNA relative expression were lower in cancer cells than in immune cells." (PMID 35866375, 2022). "In brief, DUSP1, ZFP36, SLC2A3, HMGB1, STAT3, MT3, and ALOX5 were all FRGs that might be involved in cancer development and immune regulation." (PMID 36131791, 2022). "This is consistent with the role of ALOX5 in many other cancers." (PMID 34121352, 2021). "Tumoricidal action of PUFAs on colorectal LoVo and RKO cancer cells in vitro was associated with increased formation of LXA4, decreased synthesis of PGE2 and LTB4 and suppressed expression of COX-2, ALOX5, mPGES, whereas 5-FU produced contrasting actions on these indices." (PMID 25886460, 2015). "We speculate the role of ALOX5 in cancer to be cancer type‐specific." (PMID 34121352, 2021). "ALOX5 is one of the important members of the ALOX family, which is essential for ferroptosis of cancer cells." (PMID 39850123, 2025). "Triple targeting of ALOX5, COX-2 and double mutant EGFR by novel quinazolinone tethered phenyl urea derivatives demonstrate anti-inflammatory and anti-cancer activities in numerous cancer cell lines, not limited to BT-459 breast cancer cell line." (PMID 38612771, 2024). "Some studies have demonstrated that arachidonate 5-lipoxygenase (ALOX5), and its metabolites can directly affect cancer cell dynamics by promoting proliferation or survival." (PMID 39766805, 2024). "In summary, we confirmed our previously identified methylation biomarkers ALOX5, TRPS1 and Chromosome 16 as well as our protein biomarkers CXCL16 and TGFBI to discriminate UCa from cancer-free controls in a large and independent collective." (PMID 39587670, 2024). "The products of 5-LOX/ALOX5 activity induce proliferation and self-renewal of GBM cancer stem cells." (PMID 36765904, 2023).
cancer (continued). "On the other hand, growing body of evidence indicates that arachidonate 5-lipoxygenase (ALOX5) is a crucial regulator of inflammation and cancer pathogenesis." (PMID 25886460, 2015). "For example, ALOX12 was seen to promote ferroptosis in cancer cells, while the ALOX15 was seen to have a role in mediating RSL3-induced ferroptosis in various cells, including neurons, and ALOX5 was also observed to be activated in erastin and RSL3-induced ferroptosis in cancer cells." (PMID 39721496, 2025). "In addition, down-regulation of ALOX5, MGST2, and MGST3 genes using specific siRNAs also decreased platelet-induced cancer cell wound closure and cell migration rate." (PMID 36293074, 2022). "Recently we reported that inhibition of arachidonate-5-lipoxygenase (5-Lox) by gene-targeting or by chemical inhibitors down-regulates expression and function of c-Myc selectively in cancer cells, but spares c-Myc activity in normal, non-cancer cells." (PMID 32313135, 2020). "However, upregulation of Alox5 in neutrophils treated with c-Met high CM was not significant in our RNA sequencing data, suggesting that neutrophils are able to promote cancer stemness through multiple pathways." (PMID 37174093, 2023). "ALOX5 is a non-heme iron-containing dioxygenase that encodes lipoxygenase and metabolizes AA into hydroperoxyderivatives (5-HPETE) and further into 5-hydroxyeicosatetraenoic acid (5-HETE), conferring growth, invasion, and chemopreventive advantage in cancer cells." (PMID 36777735, 2023). "The increased TFRC, PHKG2, FADS2, NOX1, and reduced ALOX5 levels in LUSC tissues were reported in the present study, and scRNA-seq analysis showed that the levels of the five dysregulated genes were mainly influenced by cancer cells rather than immune cells." (PMID 35866375, 2022).